FOXP3 (forkhead box P3)
Diseases named in the same sentence as FOXP3 in open-access papers (continued):
Sharing a sentence is not in itself a finding about the gene and the disease.
VKH syndrome (1 paper, 2015). "We applied the iPLEX system (Sequenom) and PCR-RFLP measurements to successfully evaluate 25 SNPs at TBX21, GATA3, Rorc and Foxp3 genes in an independent cohort containing 406 BD patients, 401 VKH syndrome patients and 613 healthy controls." (PMID 25873156, 2015). "Our study showed that high CNVs of Rorc and low CNVs of Foxp3 confer risk for BD but not for VKH syndrome." (PMID 25873156, 2015). "The results showed that a high CNV of Rorc and a low CNV for Foxp3 were associated with the susceptibility with BD but not with VKH syndrome in a Chinese Han population." (PMID 25873156, 2015). "The tested 25 SNPs in TBX21, GATA3, Rorc and Foxp3 did not associate with BD and VKH syndrome." (PMID 25873156, 2015).
Yersiniae infections (1 paper, 2017). "The role of immunoregulatory Foxp3+ Tregs and proinflammatory Th17 cells in combatting acute Yersiniae infections is only incompletely understood." (PMID 28378044, 2017).
tumor (4,137 papers, 2006 to 2026). "Transcriptomic profiling further revealed elevated Cd8a and Ifng (markers of cytotoxic T cell infiltration/activity) alongside reduced Foxp3 (Tregs), Cd163 (M2-polarized tumor-associated macrophages), and Tgfb1 (immunosuppressive cytokine) in KO tumors." (PMID 41144132, 2025). "The presence of these regulatory γδ T cells within the tumor is associated with increased infiltration of FOXP3+ regulatory T cells and decreased presence of cytotoxic CD8+ T cells." (PMID 41550427, 2025). "Reports have shown a positive association between B7-H3 expression in tumor cells and vasculature with FOXP3+ cell infiltration." (PMID 40801642, 2025). "A significant association was observed between FOXP3 expression and tumor stage (p = 0.028, Kruskal–Wallis test)." (PMID 40806346, 2025). "In this study, we also observed a significant reduction in tumor-infiltrating Tregs (CD4+Foxp3+ T cells) in GSDMD-deficient or DSF-treated mice, presumably due to IL-2 reduction (data not shown)." (PMID 40759573, 2025). "FOXP3, a transcription factor linked to immunosuppression within the tumor microenvironment, also showed a marked decline in expression." (PMID 41301890, 2025). "A study analyzing 680 NSCLC resection specimens revealed that tertiary lymphoid structures (TLS) correlate with plasma cell (CD138+) and lymphocyte (CD3+, CD8+, FOXP3+) infiltration, while higher tumor mutational burden predicts increased peripheral TLS." (PMID 40642092, 2025). "Immunofluorescence assays corroborated these findings, revealing a reduced percentage of CD86+ M1 macrophages and an increased percentage of CD163+ M2 macrophages and CD4+Foxp3+ Treg cells in mutated tumor tissues." (PMID 40384867, 2025). "Multiplex immunohistochemical staining (GPC3, CD4, Foxp3) revealed distinct tumor immune microenvironments between risk groups." (PMID 40533802, 2025). "Tumor-associated FOXP3 competitively binds NF-κB p65, reducing its transcriptional activation of the tumor suppressor p21 and promoting cancer cell proliferation." (PMID 41229433, 2025). "Clinical data further showed that co-infiltration of Foxp3+ Tregs and CAFs in tumor stroma was significantly associated with poor prognosis." (PMID 40534854, 2025). "Co-culture experiments showed that TBX21-deficient tumor cells reduced the induction of CD25+Foxp3+ Treg cells from activated CD4+ T cells." (PMID 41573646, 2025). "Specifically, the Th2-like (Gata3hi) cluster was overwhelmingly populated by Foxp3-degraded Treg cells from Foxp3AIDR26TIR1(F74G) mice, suggesting that Foxp3 loss preferentially skews tumor Treg cells toward a Th2-like state." (PMID 40470210, 2025). "Conversely, CAFs are positively correlated with the cumulative density of regulatory T cells (Tregs) (Foxp3+), M2 tumor‐associated macrophages (TAMs) (CD163+), and potential Treg‐inducing immune cells (CD80+)." (PMID 39928309, 2025). "A recent study on 354 clinical samples (including tumor and normal tissues) presented that high FoxP3 expression indeed associates with better survival in OSCC patients but such prediction requires several considerations." (PMID 41511327, 2025). "Declining FOXP3 expression correlated with advancing tumor stages, and low FOXP3 expression was significantly associated with poor survival in advanced stage III–IV tumors (MMA: p = 0.001, TCGA: p = 0.015), but not early-stage tumors." (PMID 40806346, 2025). "We observed that low FOXP3 expression was significantly associated with worse overall survival, tumor recurrence and larger tumor size in our experimental HPV-negative OSCC cohort (MMA), which was validated by the TCGA HPV-negative cohort." (PMID 40806346, 2025). "At univariate analysis, the presence of weight loss, symptoms at diagnosis, and extended stage were significantly associated with a worse OS, while the presence of FOXP3+ TILs in tumor specimens associated with a significantly better OS." (PMID 40255421, 2025).
tumor (continued). "As the inflammatory response intensifies, the immune environment acquires a pro-tumorigenic nature by attracting tumor-associated macrophages, myeloid-derived suppressor cells, and FOXP3+Tregs, thus overcoming the Th1 response." (PMID 40270290, 2025). "Regulatory T cells (Tregs) are typically characterized as thymus-derived CD4+ CD25+ FOXP3+ T cells, which play a crucial role in suppressing tumor-associated antigen-specific activation within tumor-draining lymph nodes." (PMID 40432130, 2025). "In the context of cancer, FOXP3 is often associated with the immunosuppressive tumor microenvironment (TME), as its expression correlates with increased Treg infiltration, leading to the inhibition of anti-tumor immunity." (PMID 39883234, 2025). "The presence of Th1 CD4+ T-cells and cytotoxic CD8+ T-cells in the tumor microenvironment has been associated with an improved prognosis, while FOXP3+ regulatory T-cells are associated with the downregulation of the immune response and a poorer prognosis." (PMID 40362529, 2025). "Specifically, the TH2-like (Gata3hi) cluster was overwhelmingly populated by Foxp3-degraded Treg cells from Foxp3AIDR26TIR1(F74G) mice, suggesting that Foxp3 loss preferentially skewed tumor Treg cells toward a TH2-like state." (PMID 41062655, 2025). "FOXP3 has been implicated in tumor-driven immune tolerance, whereas EGFR is a key oncogenic driver of proliferation and chemoresistance." (PMID 41301890, 2025). "Low FOXP3 expression was significantly associated with tumor stage (MMA: p = 0.028, TCGA: p = 0.025) and poor overall survival (MMA: p = 0.0004, TCGA: p = 0.019) in both cohorts." (PMID 40806346, 2025). "This immune profile, influenced by host genetic variants such as FOXP3 and HLA‐G polymorphisms, fosters a tumor microenvironment that favors immune evasion, epithelial‐mesenchymal transition (EMT), and metastasis." (PMID 41263059, 2025). "FOXP3 suppresses HCC cell proliferation and invasion, likely through the TGF-β/Smad2/3 signaling pathway, although the Δ3,4-FOXP3 variant shows reduced tumor-inhibiting effects." (PMID 40438106, 2025). "The TCGA validation cohort revealed that FOXP3 expression was significantly associated with tumor stage (p = 0.025), and tumor size (p = 0.048)." (PMID 40806346, 2025). "BTLA is expressed at high levels on tumor-infiltrating Tregs, and its engagement has been associated with upregulation of FOXP3, CD25, and CTLA-4—hallmarks of highly suppressive Treg phenotypes." (PMID 41471273, 2025). "PT-112 combined with ICBs achieved tumour elimination, enhanced cytotoxic T lymphocytes (CTLs) infiltration and reduced immunosuppressive CD25+FOXP3+ regulatory T-cells (Tregs) and tumour-associated macrophages (TAMs) in the TME." (PMID 40160356, 2025). "These include CD4, FOXP3 positive regulatory T-lymphocytes (Tregs), myeloid derived suppresser cells (MDSCs) recruited from the bone marrow and tumour-associated macrophages." (PMID 40427006, 2025). "Here, we demonstrated that a high density of FOXP3‐positive cells or a high FOXP3+/CD4+ cell ratio around tumor cells is associated with a poor response to BCG treatment for bladder CIS." (PMID 40084633, 2025). "We also found that mice with Opn-deficient Foxp3+ Tregs have enhanced anti-tumor immunity and reduced tumor burden, associated with an unstable Treg phenotype, paralleled by reduced Foxp3 expression in tumor-infiltrating lymphocytes." (PMID 39272810, 2024). "This analysis showed that the presence of UPP1high tumor cells was significantly positively associated with FOXP3+ regulatory T cells (Tregs), MMP11+ cancer-associated fibroblasts (CAFs), LAG3 + PDCD1 + CD8+ exhausted T cells, and M2-like SPP1+ macrophages." (PMID 38331898, 2024). "-Elevated level of CD8+ T cells infiltration in tumor accompanied by an increase in the transcript expression encoding to cytotoxic activity.- Upregulation of PD-L1 and downregulation of FOXP3." (PMID 38533510, 2024).
tumor (continued). "This seems to be supported by the association of the multifocal distribution of FoxP3+ cells with tumor-related death and shorter survival, suggesting a prognostic association of Tregs." (PMID 38672372, 2024). "High NLR has been significantly associated with lower tumor-infiltrating lymphocytes (TILs) and correlated with a higher proportion of FOXP3+ T-cells in TILs." (PMID 39628488, 2024). "The biological activity of VTCN1 is associated with inflammatory CD4+ T-cell responses and VTCN1- expressing tumor-associated macrophages and FoxP3+ regulatory T cells (T regs) within the tumor microenvironment." (PMID 39116105, 2024). "In the stroma of patients with NSCLC, the expression of FOXP3+ tumor-infiltrating lymphocytes was associated with expression of YTHDF1 and YTHDF2." (PMID 38674427, 2024). "At the same time, induced release of MUC16c into the cytoplasm also promotes the secretion of IL-6, which activates the JAK2/STAT3 pathway, promotes the expression of Foxp3 in tumor tissues and the abundance of tumor-associated regulatory T cells (Tregs)." (PMID 38758220, 2024). "We show that administration of a Zn-deficient diet suppresses tumor burden and increases Th1 cells while suppressing Foxp3+ Treg cells." (PMID 39247196, 2024). "Stratifying regions by MSH6 labeling revealed a clear increase in infiltrating CD8-positive cytotoxic T cells, CD20-positive B cells, CD4-positive T cells and FoxP3-positive Treg cells in MSH6-deficient tumor regions." (PMID 38956208, 2024). "We found that tumor tissues with high expression of RANK or CCL20 were strongly associated with enhanced FOXP3 expression." (PMID 38902257, 2024). "This highlights the mechanism underlying low methylation of FOXP3-TSDR in tumor-infiltrating CD4+ T cells in patients with CRC." (PMID 38331927, 2024). "Our experiments indicated that high Zn intake increases the frequency of tumor-infiltrating Foxp3+ Tregs while Zn deficiency or chelation reduces the frequency of tumor-infiltrating Foxp3+ Tregs." (PMID 39247196, 2024). "Tumor-infiltrating Forkhead box P3+ (FoxP3) T regulatory cells have, likewise, been associated with improved survival in MIBC." (PMID 39337385, 2024). "Correlation analysis showed that among 18 predominant bacterial genera of the tumor microbiome, Acinetobacter and Dietzia were inversely correlated with the abundance of FoxP3+ cells, and Pelomonas was negatively associated with GZMA level." (PMID 39554133, 2024). "Inhibition of tumor growth in BC mouse models after systemic treatment with SI-2, which is associated with a decrease of FOXP3+ cells and increase of cytotoxic immune cells (CD8+ T cells, NK cells) and proinflammatory cytokines in the TME." (PMID 38698860, 2024). "Our data showed that the frequency of tumor-infiltrated Foxp3+ Tregs was decreased in the mice that were given a Zn-deficient diet while a higher Zn intake increased the frequency of Foxp3+ Tregs." (PMID 39247196, 2024). "A previous study showed that there was an association between FDG uptake and the expression of Foxp3-regulatory T cells (Tregs) in the tumor microenvironment of NSCLC." (PMID 39238640, 2024). "Together with Tregs, the upregulation of PD-L1 expression in tumor cells induced by cancer-Foxp3 in PDAC increases immune evasion and causes the immunosuppressive microenvironment." (PMID 38672552, 2024). "High infiltration of FoxP3+Treg is associated with better prognosis and can be used in combination with tumor staging and histological grading for prognosis evaluation of HNSCC patients." (PMID 38365684, 2024). "Our data showed that the CD8+ TILs/CD4+CD25+FOXP3+ Treg ratio was associated with improved OS and inversely correlated with tumor invasion and metastasis, suggesting that immune balance affects prognosis." (PMID 39264227, 2024).
tumor (continued). "Foxp3 was significantly associated with tumor TNM stage (χ2 = 22.025, p <0.01), vascular cancer emboli (χ2 = 5.089, p =0.022), neural invasion (χ2 = 5.289, p =0.018), lymph node metastasis (χ2 = 15.121, p =0.003), and distant metastasis (χ2 = 6.759, p =0.007)." (PMID 39104717, 2024). "Foxp3-expressing regulatory T (Treg) cells suppress effective tumor immunity and are associated with poor prognosis in patients with cancer." (PMID 38384466, 2024). "Only PD-L1 IC and CPS > 10% was associated with higher Foxp3+CD4+ T cells infiltration level in tumour tissue." (PMID 38541208, 2024). "The biological activity of B7-H4 is associated with a reduced inflammatory CD4 T cell response, and the correlation between tumor-associated macrophages expressing B7-H4 and regulatory T cells (Tregs) expressing FoxP3 in the tumor microenvironment." (PMID 38612764, 2024). "MMP12 has been implicated in increasing FOXP3 Treg infiltration into tumor tissues, thereby enhancing tumor proliferation and immune evasion in HCC." (PMID 38535990, 2024). "Among TILs, the effector immune cells (CD8+T cells and Th1/CD4 + T cells) are associated with tumor immune elimination, while inhibitory phenotypes, such as CD4 + FoxP3 + T cells (Treg), are associated with tumor progression." (PMID 38397152, 2024). "Diverse signals can trigger cell differentiation or morphological changes in vivo, as seen in the immunofluorescence staining results showing the loss of c-FOXP3+ cells in parts of the tumor tissue formed by c-FOXP3+E-Cadherin− cells." (PMID 38047300, 2024). "Accordingly, loss of FOXP3 in our murine tumor model led to drastically fewer metastases to the lung and liver compared with the wild-type counterpart." (PMID 39099201, 2024). "Our data demonstrated that pre-existing stromal macrophages and CD3 + FoxP3 + T cells were significantly associated with the residual tumor existed in the resected lymph nodes." (PMID 38802821, 2024). "If a decrease in PD-L1 mediated by loss of FOXP3 contributed to the immune-dependent suppression of tumor growth, we would predict an increase in infiltration of CD8+ cells." (PMID 39099201, 2024). "Cytoplasmic FOXP3+ tumor cells were reported previously, and they were associated with worse prognosis in patients with breast cancer." (PMID 38898200, 2024). "In contrast, a significant enrichment of CD4+FOXP3+ regulatory T (Treg) cells is observed within tumor-associated TLS compared to peritumoral ones, suggesting a potential for immune suppression." (PMID 39198425, 2024). "IDO expression is associated with tumor-infiltrating forkhead box P3 positive regulatory T-cells (FoxP3+ Tregs) and is negatively associated with CD8+ cytotoxic T-cells." (PMID 38426097, 2024). "Taken together, these observations indicated that Zn-mediated tumor progression is linked with Foxp3+ Tregs." (PMID 39247196, 2024). "It was earlier suggested that Foxp3+ Tregs and tumor-associated macrophages (TAMs) were found to be present in the tumor microenvironment (TME) and suggested to support tumor growth by suppressing antitumor immune response." (PMID 39247196, 2024). "On the other hand, higher PD-L1+ lymphocyte infiltration in tumour stroma was associated only with higher Foxp3+CD4+ T cell infiltration in islets and lower M1 macrophage infiltration level in tumour stroma." (PMID 39409156, 2024). "Our study demonstrated that FoxP3 distribution was associated with tumor-related death and survival, while the CD20 count was associated with metastasis." (PMID 38672372, 2024). "The occurrence of an immunosuppressive TME promotes tumor growth and progression; for this reason, the FOXP3+ Tregs presence has been associated with a poor prognosis in various solid tumors, including NSCLC (HR: 3.91 and p < 0.001)." (PMID 38674427, 2024).